SLC4A8 (solute carrier family 4 member 8)
Description:
Mediates electroneutral sodium- and carbonate-dependent chloride-HCO3(-) exchange with a Na(+):HCO3(-) stoichiometry of 2:1. Plays a major role in pH regulation in neurons (By similarity). Mediates sodium reabsorption in the renal cortical collecting ducts (By similarity).
Synonyms: NBC3; NDCBE
Tractability: Antibody: UniProt places it where antibodies can reach, with high confidence; its Gene Ontology location is reachable by antibodies, with high confidence; UniProt predicts a signal peptide or a membrane-spanning region; the Human Protein Atlas places it where antibodies can reach. PROTAC: ubiquitination databases record sites on it; its protein half-life has been measured.
Safety:
Unwanted effects reported when the protein is acted on. In parentheses: how it was acted on, where the effect was seen, and who reports it.
alcoholism (source: ClinPGx)
Gene: Protein-coding gene on chromosome 12 (51,391,317 to 51,515,763, forward strand). Ensembl gene ENSG00000050438.
Subcellular location: Apical cell membrane; Basolateral cell membrane; Cytoplasmic vesicle, secretory vesicle, synaptic vesicle membrane; Cell membrane (Isoform 1); Cell membrane (Isoform 3); Cell membrane (Isoform 4); Cell membrane (Isoform 5)
Subcellular location (Human Protein Atlas): Plasma membrane
Pathways (Reactome):
Transport of small molecules: Bicarbonate transporters
Gene Ontology:
Molecular function: bicarbonate transmembrane transporter activity; chloride transmembrane transporter activity; sodium ion transmembrane transporter activity; sodium:bicarbonate symporter activity; solute:inorganic anion antiporter activity; identical protein binding; monoatomic anion transmembrane transporter activity; sodium,bicarbonate:chloride antiporter activity
Biological process: bicarbonate transport; chloride transmembrane transport; regulation of intracellular pH; regulation of membrane potential; sodium ion transmembrane transport; modulation of chemical synaptic transmission; positive regulation of synaptic vesicle exocytosis; transport across blood-brain barrier; basolateral protein secretion; monoatomic anion transport; regulation of synaptic vesicle exocytosis
Cellular component: apical plasma membrane; dendrite; plasma membrane; asymmetric synapse; axon terminus; basolateral plasma membrane; glial cell projection; glutamatergic synapse; hippocampal mossy fiber; membrane; neuron projection; neuronal cell body membrane; presynapse; presynaptic membrane; symmetric synapse; synaptic vesicle; terminal bouton; synaptic vesicle membrane
Genetic constraint (gnomAD): Loss-of-function variants: 31 observed, 90.58 expected, observed/expected ratio (o/e) 0.34, 90% interval 0.26 to 0.46. The upper end of that interval is the gene's LOEUF score, 0.46, which puts it in group 2 of 6, group 1 being the genes least tolerant of losing a copy. Missense variants: 702 observed, 1,136 expected, observed/expected ratio (o/e) 0.62, 90% interval 0.58 to 0.66. Synonymous variants: 384 observed, 410.18 expected, observed/expected ratio (o/e) 0.94, 90% interval 0.86 to 1.02.
Homologues: Orthologues: chimpanzee SLC4A8 (99% identical), macaque SLC4A8 (99% identical), pig SLC4A8 (98% identical), guinea pig SLC4A8 (98% identical), mouse Slc4a8 (96% identical), rat Slc4a8 (96% identical), dog SLC4A8 (95% identical), rabbit SLC4A8 (91% identical), tropical clawed frog slc4a8 (86% identical), zebrafish slc4a8 (77% identical), Drosophila melanogaster Ndae1 (51% identical), Caenorhabditis elegans abts-1 (48% identical), and 2 more. Paralogues in human: SLC4A10 (77% identical), SLC4A7 (73% identical), SLC4A4 (52% identical), SLC4A5 (47% identical), SLC4A9 (40% identical), SLC4A2 (36% identical), SLC4A3 (35% identical), SLC4A1 (30% identical), SLC4A11 (20% identical).
Diseases named in the same sentence as SLC4A8 in open-access papers:
SLC4A8 is named in the same sentence as 11 diseases in open-access papers, as found by Europe PMC text mining. Sharing a sentence is not in itself a finding about the gene and the disease. The quoted sentences say what the papers report.
cholangiocarcinoma (1 paper, 2020). A carcinoma that arises from the intrahepatic biliary tree (intrahepatic cholangiocarcinoma) or from the junction, or adjacent to the junction, of the right and left hepatic ducts (hilar cholangiocarcinoma). "Inhibition of NDCBE in cholangiocarcinoma cells, a product of the SLC4A8 gene downregulated in our study, decreases proliferation and induces apoptosis." (PMID 32260415, 2020).
SLC4A8 also shares sentences with these, for which no sentence is quoted: ovarian carcinoma (2 papers); autism (1); Gitelman syndrome (1); glioma (1); Hydrocephalus (1); Hypokalemia (1); melanoma (1); neurological disorder (1); schizophrenia (1); tumor (1).